ALKBH6 (alkB homolog 6, nucleotide demethylase)
Description:
Probable Fe(2+)/2-oxoglutarate-dependent dioxygenase involved in oxidative demethylation of nucleic acids. Binds nucleic acids with a preference for ssDNA or ssRNA to other types of DNAs. May play a role in nucleic acid damage repair.
Synonyms: ABH6; MGC15677
Tractability: Small molecule: a structure with a bound ligand is known. PROTAC: ubiquitination databases record sites on it; its protein half-life has been measured.
Gene: Protein-coding gene on chromosome 19 (36,009,120 to 36,014,297, reverse strand). Ensembl gene ENSG00000239382.
Subcellular location: Cytoplasm; Nucleus
Subcellular location (Human Protein Atlas): Nucleoplasm; Focal adhesion sites
Gene Ontology:
Molecular function: 2-oxoglutarate-dependent dioxygenase activity; protein binding
Cellular component: cytoplasm; nucleus
Genetic constraint (gnomAD): Loss-of-function variants: 22 observed, 27.27 expected, observed/expected ratio (o/e) 0.81, 90% interval 0.57 to 1.15. The upper end of that interval is the gene's LOEUF score, 1.15, which puts it in group 5 of 6, group 1 being the genes least tolerant of losing a copy. Missense variants: 263 observed, 278.19 expected, observed/expected ratio (o/e) 0.95, 90% interval 0.85 to 1.05. Synonymous variants: 156 observed, 126 expected, observed/expected ratio (o/e) 1.24, 90% interval 1.09 to 1.41.
Homologues: Orthologues: chimpanzee ALKBH6 (99% identical), macaque ALKBH6 (98% identical), pig ALKBH6 (93% identical), dog ALKBH6 (92% identical), rabbit ALKBH6 (92% identical), guinea pig ALKBH6 (91% identical), mouse Alkbh6 (91% identical), rat Alkbh6 (90% identical), tropical clawed frog alkbh6 (59% identical), zebrafish alkbh6 (55% identical), Drosophila melanogaster CG6144 (44% identical), Caenorhabditis elegans B0564.2 (38% identical). Paralogues in human: ALKBH8 (23% identical), TRMT9B (9% identical).
Diseases named in the same sentence as ALKBH6 in open-access papers:
ALKBH6 is named in the same sentence as 11 diseases in open-access papers, as found by Europe PMC text mining. Sharing a sentence is not in itself a finding about the gene and the disease. The quoted sentences say what the papers report.
pancreatic cancer (3 papers, 2021 to 2025). "A study showed that a deficiency of ALKBH6 in human pancreatic cancer (PC) cells increased alkylation-induced DNA damage and thus significantly reduced cell survival." (PMID 37007161, 2023). "In particular, the loss of ALKBH6 in human pancreatic cancer cells increases alkylating agent-induced DNA damage and significantly decreases cell survival." (PMID 33897761, 2021). "Considering the clinical relevance of our study, ALKBH6 is significantly overexpressed in pancreatic cancer and is associated with favorable overall survival." (PMID 33897761, 2021). "Our results show that co-occurrence of ALKBH6 overexpression and loss of tumor suppressor genes status is critical for pancreatic cancer progression and negatively impacts patient overall survival." (PMID 33897761, 2021). "Heterologous expression of ALKBH6 in Alkb-deficient E. coli strain was reported to suppress MMS-induced cytotoxicity and silencing of ALKBH6 in pancreatic cancer cell lines was shown to promote cell survival following exposure to alkylating agents." (PMID 40885392, 2025). "In contrast, bioinformatics analysis of the The Cancer Genome Atlas (TCGA) database showed that overexpression of ALKBH6 led to better survival outcomes in pancreatic cancer patients." (PMID 37007161, 2023). "To correlate our findings to human pancreatic cancer, we quantified the expression data of ALKBH6 in pancreatic cancer using The Cancer Genome Atlas database (TCGA)." (PMID 33897761, 2021). "Overall, our data suggest that ALKBH6 is required to maintain the integrity of the genome and promote cell survival of pancreatic cancer cells." (PMID 33897761, 2021). "We observed that 28% of pancreatic cancer patients overexpressed mRNA of ALKBH6 in tumor tissue samples relative to normal pancreatic tissue." (PMID 33897761, 2021). "In this study, overexpression of ALKBH6 genes improves pancreatic cancer survival rates, compared to pancreatic cancer patients with low expression." (PMID 33897761, 2021). "Our results also demonstrated that MMS treatment compromises the survival of pancreatic cancer cells, suggesting the involvement of ALKBH6 in DNA repair." (PMID 33897761, 2021). "Specifically, an approximate 4% genetic alteration and 28% mRNA overexpression of ALKBH6 is detected in pancreatic cancer cells compared to other ALKBH genes." (PMID 33897761, 2021). "In particular, our data show that the loss of ALKBH6 increased MMS-induced DSBs and enhanced the cytotoxicity of MMS in human pancreatic cancer cells." (PMID 33897761, 2021). "In summary, our results suggest that ALKBH6 is involved in protecting pancreatic cancer from alkylating-induced DNA damage and promotes cell survival." (PMID 33897761, 2021). "Furthermore, bioinformatic analysis of the TCGA database showed that overexpression of ALKBH6 provided better survival outcomes for pancreatic cancer patients." (PMID 37007161, 2023). "Moreover, high expression of ALKBH6 in pancreatic cancer tissue was correlated with favorable overall patient survival." (PMID 33897761, 2021). "Here, we tested whether ALKBH6 plays a significant role in preventing alkylating DNA damage and decreasing genomic instability in pancreatic cancer cells." (PMID 33897761, 2021). "Furthermore, in silico analysis from The Cancer Genome Atlas (TCGA) database suggests that overexpression of ALKBH6 provides better survival outcomes in patients with pancreatic cancer." (PMID 33897761, 2021). "To determine whether ALKBH6 protects pancreatic cancer cells from accumulating alkylating agent-induced DNA damage, we performed siRNA-mediated silencing of ALKBH6 in BXPC3 and MIA-PaCa-2 pancreatic cancer cell lines and performed an immunofluorescence co-localization assay." (PMID 33897761, 2021).
pancreatic cancer (continued). "However, siRNA-silenced ALKBH6 leads to the accumulation of cells in the G2/M phase of the cell cycle suggesting that ALKBH6 may contribute to the mitotic cellular growth of pancreatic cancer cells." (PMID 33897761, 2021). "In this study, we show that human ALKBH6 is required to prevent genomic instability and to prevent the MMS-induced cytotoxicity seen in pancreatic cancer." (PMID 33897761, 2021). "Our data show that siRNA silencing of ALKBH6 in pancreatic cancer cell lines increases DSBs and sensitivity to MMS but not MNU." (PMID 33897761, 2021). "Altogether, these results suggest that ALKBH6 is involved in maintaining genomic integrity during SN2 alkylating agent-mediated DNA damage, and also provides a more favorable prognosis in the overall survival of pancreatic cancer patients." (PMID 33897761, 2021). "To determine whether ALKBH6 promotes cell survival and cellular growth, we performed siRNA-mediated silencing of ALKBH6 in BXPC3 and MIA-PaCa-2 pancreatic cancer cell lines and performed a clonogenic survival assay." (PMID 33897761, 2021).
breast carcinoma (1 paper, 2022). "It is short of direct proof about the relationship between ALKBH family and stage or subclasses in breast cancer, this study provided that ALKBH1, ALKBH4, and ALKBH6 might be associated with later stage, while ALKBH8 was relative to an earlier stage." (PMID 35980268, 2022). "With compared the expression of ALKBH family members in breast cancer and normal samples, the up-regulation was ALKBH1, ALKBH2, ALKBH4, ALKBH6, ALKBH7, and others such as ALKBH3, ALKBH8, FTO was down-regulation." (PMID 35980268, 2022).
gastric cancer (1 paper, 2024). A primary or metastatic malignant neoplasm involving the stomach. "Conversely, ALKBH2, ALKBH3, ALKBH5, ALKBH6, and ALKBH7 showed low expression in gastric cancer tissues." (PMID 38902235, 2024).
head and neck squamous cell carcinoma (1 paper, 2021). A squamous cell carcinoma that arises from any of the following anatomic sites: lip and oral cavity, nasal cavity, paranasal sinuses, pharynx, larynx, and salivary glands. "In addition, a high level of ALKBH6 expression has been detected in adenocarcinomas of other organs, such as head and neck squamous cell carcinoma, malignant melanoma, and renal cell carcinoma, with favorable overall survival as well." (PMID 33897761, 2021).
low grade glioma (1 paper, 2021). A grade I or grade II glioma arising from the central nervous system. "In contrast, we found that the majority of tumor tissues that significantly overexpressed ALKBH6 were associated with poor overall survival in a few types of cancer including low-grade glioma (LGG) and kidney renal clear cell carcinoma (data not shown)." (PMID 33897761, 2021).
lymph node metastasis (1 paper, 2021). "At the same time, the mRNA expression levels of ALKBH2, ALKBH3, and ALKBH6 had a trend to upper expression in tumors with lymph node metastasis, although this was not significant." (PMID 34150745, 2021).
tumor (3 papers, 2021 to 2023). "The relatively high expression of ALKBH6 in tumor tissues correlate with cancer development in some cancer types, and may provide an opportunity to use ALKBH6 as a potential target for anticancer therapy." (PMID 33897761, 2021). "SOX2OT could recruit ALKBH5 and ALKBH6 to bind to SOX2 and demethylate the SOX2 transcript and subsequent SOX2 up-regulation, thereby regulating tumour cell apoptosis, cell proliferation, and TMZ resistance." (PMID 38055673, 2023). "On account of the advance stage which indicates progression, ALKBH1, ALKBH4, ALKBH6, and ALKBH8 may be the potential biomarker for predicting tumor progression." (PMID 35980268, 2022). "Moreover, our TCGA data analysis shows that a majority of tumor tissues significantly overexpress ALKBH6, as compared to normal tissue, and show poor overall survival in the selected types of human cancers, thus suggesting a pro-carcinogenic role of these proteins." (PMID 33897761, 2021).
cancer (2 papers, 2021 to 2023). A tumor composed of atypical neoplastic, often pleomorphic cells that invade other tissues. "Nevertheless, there is evidence that ALKBH6 plays an essential role in maintaining genomic integrity, particularly in cancer." (PMID 37007161, 2023). "It suggests that ALKBH6 may be essential in maintaining genomic integrity, especially in cancer." (PMID 37007161, 2023).
ALKBH6 also shares sentences with these, for which no sentence is quoted: adenocarcinoma (1 paper); malignant melanoma (1); renal cell carcinoma (1).